Y_RNA (Y RNA )
Gene: Miscellaneous RNA gene on chromosome 19 (40,342,329 to 40,342,441, forward strand). Ensembl gene ENSG00000206925.
Homologues: Orthologues: chimpanzee Y_RNA (100% identical), macaque Y_RNA (95% identical). Paralogues in human: RNY1 (88% identical), Y_RNA (86% identical), Y_RNA (85% identical), Y_RNA (84% identical), Y_RNA (83% identical), RNY1P11 (82% identical), Y_RNA (82% identical), RNY1P7 (81% identical), RNY1P8 (81% identical), Y_RNA (81% identical), RNY1P10 (80% identical), Y_RNA (80% identical), and 96 more.